HSPA1B (heat shock protein family A (Hsp70) member 1B)
Description:
Molecular chaperone implicated in a wide variety of cellular processes, including protection of the proteome from stress, folding and transport of newly synthesized polypeptides, activation of proteolysis of misfolded proteins and the formation and dissociation of protein complexes. Plays a pivotal role in the protein quality control system, ensuring the correct folding of proteins, the re-folding of misfolded proteins and controlling the targeting of proteins for subsequent degradation. This is achieved through cycles of ATP binding, ATP hydrolysis and ADP release, mediated by co-chaperones. The co-chaperones have been shown to not only regulate different steps of the ATPase cycle, but they also have an individual specificity such that one co-chaperone may promote folding of a substrate while another may promote degradation. The affinity for polypeptides is regulated by its nucleotide bound state. In the ATP-bound form, it has a low affinity for substrate proteins. However, upon hydrolysis of the ATP to ADP, it undergoes a conformational change that increases its affinity for substrate proteins. It goes through repeated cycles of ATP hydrolysis and nucleotide exchange, which permits cycles of substrate binding and release. The co-chaperones are of three types: J-domain co-chaperones such as HSP40s (stimulate ATPase hydrolysis by HSP70), the nucleotide exchange factors (NEF) such as BAG1/2/3 (facilitate conversion of HSP70 from the ADP-bound to the ATP-bound state thereby promoting substrate release), and the TPR domain chaperones such as HOPX and STUB1. Maintains protein homeostasis during cellular stress through two opposing mechanisms: protein refolding and degradation. Its acetylation/deacetylation state determines whether it functions in protein refolding or protein degradation by controlling the competitive binding of co-chaperones HOPX and STUB1. During the early stress response, the acetylated form binds to HOPX which assists in chaperone-mediated protein refolding, thereafter, it is deacetylated and binds to ubiquitin ligase STUB1 that promotes ubiquitin-mediated protein degradation. Regulates centrosome integrity during mitosis, and is required for the maintenance of a functional mitotic centrosome that supports the assembly of a bipolar mitotic spindle. Enhances STUB1-mediated SMAD3 ubiquitination and degradation and facilitates STUB1-mediated inhibition of TGF-beta signaling. Essential for STUB1-mediated ubiquitination and degradation of FOXP3 in regulatory T-cells (Treg) during inflammation. (Microbial infection) In case of rotavirus A infection, serves as a post-attachment receptor for the virus to facilitate entry into the cell.
Synonyms: HSP70-2; HSP70.2; HSP72; HSP70-1; HSP70-1B; HSP70.1; HSPA1; HSX70
Tractability: Small molecule: a structure with a bound ligand is known; it belongs to a druggable protein family. Antibody: its Gene Ontology location is reachable by antibodies, with high confidence. Other modalities: a drug acting on it is in phase 2 or 3 trials.
Gene: Protein-coding gene on chromosome 6 (31,827,738 to 31,830,254, forward strand). Ensembl gene ENSG00000204388.
Subcellular location: Cytoplasm; Cytoplasm, cytoskeleton, microtubule organizing center, centrosome
Subcellular location (Human Protein Atlas): Annulus; Cytosol; Flagellar centriole; Vesicles; Calyx; Perinuclear theca
Pathways (Reactome):
Cellular responses to stimuli: Attenuation phase; HSF1 activation; HSF1-dependent transactivation; HSP90 chaperone cycle for steroid hormone receptors (SHR) in the presence of ligand; Mitochondrial unfolded protein response (UPRmt); Regulation of HSF1-mediated heat shock response
Immune System: Neutrophil degranulation; PKR-mediated signaling
Disease: Dengue Virus Genome Translation and Replication
Gene Ontology:
Molecular function: ATP binding; ATP hydrolysis activity; ATP-dependent protein disaggregase activity; C3HC4-type RING finger domain binding; enzyme binding; G protein-coupled receptor binding; heat shock protein binding; histone deacetylase binding; protein binding; protein folding chaperone; RNA binding; signaling receptor binding; ubiquitin protein ligase binding
Biological process: ATP metabolic process; cellular heat acclimation; cellular response to heat; mRNA catabolic process; negative regulation of apoptotic process; negative regulation of cell growth; negative regulation of cell population proliferation; negative regulation of extrinsic apoptotic signaling pathway in absence of ligand; negative regulation of inclusion body assembly; negative regulation of protein ubiquitination; positive regulation of canonical NF-kappaB signal transduction; positive regulation of erythrocyte differentiation; positive regulation of gene expression; positive regulation of interleukin-8 production; positive regulation of microtubule nucleation; positive regulation of nucleotide-binding oligomerization domain containing 2 signaling pathway; positive regulation of tumor necrosis factor-mediated signaling pathway; protein refolding; regulation of mitotic spindle assembly; regulation of protein ubiquitination; cellular response to oxidative stress; cellular response to steroid hormone stimulus; positive regulation of proteasomal ubiquitin-dependent protein catabolic process; protein stabilization
Cellular component: aggresome; blood microparticle; centriole; centrosome; cytoplasm; cytosol; extracellular exosome; focal adhesion; inclusion body; nuclear speck; nucleus; perinuclear region of cytoplasm; protein-containing complex; ribonucleoprotein complex; vesicle; endoplasmic reticulum; extracellular region; ficolin-1-rich granule lumen; mitochondrion; nucleoplasm; plasma membrane
Genetic constraint (gnomAD): Loss-of-function variants: 5 observed, 4.55 expected, observed/expected ratio (o/e) 1.1, 90% interval 0.56 to 1.85. That is too few expected variants to judge how well the gene tolerates losing a copy. Missense variants: 130 observed, 221.03 expected, observed/expected ratio (o/e) 0.59, 90% interval 0.51 to 0.68. Synonymous variants: 80 observed, 89.53 expected, observed/expected ratio (o/e) 0.89, 90% interval 0.75 to 1.08.
Homologues: Orthologues: chimpanzee HSPA1B (100% identical), dog HSP70 (99% identical), pig HSP70.2 (98% identical), rat Hspa1b (97% identical), mouse Hspa1a (95% identical), mouse Hspa1b (95% identical), Caenorhabditis elegans F44E5.4 (69% identical), Caenorhabditis elegans F44E5.5 (69% identical), Caenorhabditis elegans hsp-70 (67% identical), Drosophila melanogaster Hsp110 (30% identical), Caenorhabditis elegans hsp-110 (29% identical). Paralogues in human: HSPA1A (100% identical), HSPA1L (89% identical), HSPA8 (86% identical), HSPA2 (84% identical), HSPA6 (81% identical), HSPA5 (63% identical), HSPA9 (50% identical), HSPA4 (35% identical), HSPA4L (33% identical), HSPH1 (32% identical), HYOU1 (30% identical), HSPA14 (28% identical), and 1 more.
Diseases named in the same sentence as HSPA1B in open-access papers:
HSPA1B is named in the same sentence as 119 diseases in open-access papers, as found by Europe PMC text mining. Sharing a sentence is not in itself a finding about the gene and the disease. The quoted sentences say what the papers report.
colon cancer (7 papers, 2021 to 2025). "Interestingly, higher HSPA1A and HSPA1B expression was previously linked to poor survival in colon cancer." (PMID 38461240, 2024). "The gene HspA1B is one of the most prominent biomarkers for PC and HSPA1A and HSPA1B upregulation is associated with a poor survival in colon cancer." (PMID 35887223, 2022). "We found that increased expressions of HSPA1A1, HSPA1B, and HSPA7 were associated with poor prognosis, while that of HSPA9 was related to favorable prognosis for colon cancer patients." (PMID 34765552, 2021). "In summary, the increased expressions of HSPA1A1, HSPA1B, and HSPA7 were associated with poor prognosis, while that of HSPA9 was related to favorable prognosis for colon cancer patients." (PMID 34765552, 2021). "It was shown that HSPA1B (HR=2.745, 95%CI, 1.188-6.339, P=0.018) was an independent factor for survival in colon cancer." (PMID 34765552, 2021). "In conclusion, the increased expression of HSPA1A1, HSPA1B, and HSPA7 was associated with poor prognosis, and HSPA9 was related to favorable prognosis for colon cancer." (PMID 34765552, 2021). "Colon cancer cell lines also showed increased expression of HSPA1B and HSPA9 and decreased expression of HSPA1A and HSPA7." (PMID 34765552, 2021). "The expression difference of HSPA1A/HSPA1B/HSPA7/HSPA9 was verified in colon cancer cell lines and colonic epithelial cells." (PMID 34765552, 2021). "Our results, indicating that HSPA1B was related to poor survival of colon cancer, were consistent with previous studies." (PMID 34765552, 2021). "Univariate regression analysis was performed to explore the correlation of HSPA1A, HSPA1B, HSPA7, and HSPA9 expression with survival in colon cancer patients." (PMID 34765552, 2021). "Interestingly, post-surgery levels of PFKFB3, IL1b, HSPA1B and DDIT4 in colon cancer were increased compared to control." (PMID 36733385, 2022). "Furthermore, GO ontology analysis was performed to screen the signaling pathways related to HSPA1A, HSPA1B, HSPA7, and HSPA9 in colon cancer." (PMID 34765552, 2021).
diabetes (6 papers, 2011 to 2025). "Hspa1b, a close relative of Hspa1a, was associated to obesity, type 2 diabetes mellitus, and hyperlipidemia." (PMID 28425976, 2017). "In particular, beta cells of diabetics exhibited decreased expression of genes encoding molecular chaperones belonging to the heat shock families Hsp70 (HSPA1B, HSPA7, and HSPA8) and Hsp90 (HSP90AA1 and HSP90AB1) as well as co-chaperones (BAG3 and ST13) and nucleoporins (NDC1, NUP160, and POM121C)." (PMID 37569434, 2023). "One of the Hsp70 family chaperones concerning diabetes is HSPA1B.HSPA1B plays a crucial role in regulating proteostasis by transporting and folding synthesized polypeptides." (PMID 40533788, 2025). "Only Hspa1b and Lap3, which were determined to be up-regulated with diabetes by both DIGE and iTRAQ, were observed by multiple methods." (PMID 21249158, 2011).
schizophrenia (6 papers, 2015 to 2022). A major psychotic disorder characterized by abnormalities in the perception or expression of reality. "Among them, HSPA5 and HSPA1B have recently been shown to be potentially associated with the occurrence of anxiety, mood disorders, and schizophrenia." (PMID 35743957, 2022). "In this paper, we evaluated the association between the other four variants of the HSPA1B gene (rs6457452, rs2763979, rs539689, and rs9281590) and the susceptibility to paranoid schizophrenia." (PMID 31642026, 2020). "To conclude, our case–control study provided evidence that variants in HSPA1B gene contribute to schizophrenia susceptibility, psychopathology, and suicidal behavior in schizophrenic patients, which is a novel finding." (PMID 31642026, 2020). "This study aimed to find the potential association between HSPA1B polymorphisms and risk of paranoid schizophrenia, clinical variables of the disease, and suicidal behavior." (PMID 31642026, 2020). "We demonstrated the effects of genotypes of HSPA1B + 1267A/G polymorphism on schizophrenia psychopathology (positive PANSS scores) in our previous study." (PMID 31642026, 2020). "Another important finding of the current study was a strong significant association between the HSPA1B rs539689 polymorphism and attempted suicide in patients with schizophrenia." (PMID 31642026, 2020). "Recently, it has been proposed that HSPA1B polymorphism may be associated with schizophrenia and suicidal behavior of schizophrenic patients." (PMID 35743957, 2022). "On the contrary, a strong tendency towards statistical significance (p = 0.051) in the allelic distribution of the HSPA1B rs539689 polymorphism between patients and controls was observed in this report, and the rs539689G allele was more represented in patients with paranoid schizophrenia." (PMID 31642026, 2020). "In the present study, we performed a case–control analysis to investigate the potential association between the fourth variants of the HSPA1B gene (rs6457452, rs2763979, rs539689, and rs9281590) and the susceptibility to paranoid schizophrenia in a Caucasian Polish population." (PMID 31642026, 2020). "Our findings support that HSPA1B gene may be involved in susceptibility to schizophrenia and clinical presentation of the disease in a sex-dependent manner, and may play a role in suicidal behavior in the Polish population of schizophrenic patients." (PMID 31642026, 2020). "The genes encoding HSPA1A, HSPA1B, and HSPA1L are located in the MHC class III region of 6p21.3–22.1, which is a region implicated in susceptibility to schizophrenia." (PMID 35562887, 2022). "It should be emphasized that our study is the first analyzing the association between rs2763979, rs9281590, and rs6457452 SNPs of HSPA1B and schizophrenia." (PMID 31642026, 2020). "Further independent analyses in different populations should be performed to clarify the role of HSPA1B in the pathogenesis of schizophrenia." (PMID 31642026, 2020). "We also identified C–G–T haplotype as predisposing to schizophrenia, and demonstrated the effects of HSPA1A and HSPA1B genotypes on psychopathology and age of onset." (PMID 31642026, 2020). "Current study also showed an impact of HSPA1B rs539689 SNP on the clinical presentation of schizophrenia." (PMID 31642026, 2020). "Further studies with larger sample size and in different ethnic backgrounds are needed to clarify the role of HSPA1B in the pathogenesis of schizophrenia." (PMID 31642026, 2020). "The haplotype distribution of the four HSPA1B polymorphisms was not different between schizophrenia and control groups, and schizophrenia predisposing haplotype was not identified." (PMID 31642026, 2020). "A significant association of the HSPA1B + 1267A allele with schizophrenia development (but no psychopathology) in Koreans has also been reported." (PMID 31642026, 2020).
schizophrenia (continued). "In our previous work, we explored the possibility that HSPA1A (+190G/C), HSPA1B (+1267A/G), and HSPA1L (+2437T/C) gene polymorphisms might be involved in the susceptibility to paranoid schizophrenia and clinical presentation of the disease in the Polish population." (PMID 31642026, 2020). "According to a study of convergent functional genomics, among the most promising candidate genes known to play a role in the disorder are disrupted-in schizophrenia (DISC1), transcription factor 4 (TCF4), myelin basic protein (MBP) and heat-shock 70-kDa protein 1B (HSPA1B)." (PMID 25658856, 2015).
Alzheimer disease (5 papers, 2019 to 2025). A progressive, neurodegenerative disease characterized by loss of function and death of nerve cells in several areas of the brain leading to loss of cognitive function such as memory and language. "Previously, an association between the presence of the HSPA1B rs9281590 A2 allele and overexpression of non-cognitive abnormalities within a population affected by Alzheimer’s disease has been reported." (PMID 31642026, 2020). "It has been shown that HSPA1B also functions in the pathogenesis of other neurological conditions, such as Parkinson disease, progressive supranuclear palsy, and Alzheimer’s disease, presumably by facilitating protein folding and inhibiting apoptosis." (PMID 31447881, 2019).
breast carcinoma (5 papers, 2019 to 2023). "It has been pointed out that HSPA1B was associated with risk and poor prognosis of lung cancer, and it was involved in the tumor growth of colorectal and breast cancer." (PMID 34765552, 2021). "It indicates that the doxorubicin induces the dysregulation of hiPSC-CMs derived RAD9A, HSPA1B, GATA2, IGF2R, CD200, ERCC8, and BCL11A genes that are associated with the pathogenesis of doxorubicin-induced cardiotoxicity in breast cancer patients." (PMID 37684436, 2023). "On the other hand, MM cell exposure to GSK260614 upregulated genes such as HSPA2 and HSPA1B, which are members of the heat-shock protein family and studies have shown that breast cancer patients overexpressing HSPA2 exhibited longer survival." (PMID 33028016, 2020). "Multiple heat shock proteins, including Hsp90AA1, Hsp90AB1, TRAP1, HspA5, HspB1, HspE1, HspD1, HspA1B, HspA8, HspA9, and HspA4, were significantly upregulated in breast cancer tissue." (PMID 31921692, 2019). "Heat shock proteins showed the most significant change of all the upregulated domains, with Hsp90AA1, Hsp90AB1, TRAP1, HspA5, HspB1, HspE1, HspD1, HspA1B, HspA8, HspA9, and HspA4 identified in breast cancer tissue." (PMID 31921692, 2019). "Hsp90AA1, Hsp90AB1, TRAP1, HspA5, HspB1, HspE1, HspD1, HspA1B, HspA8, HspA9, and HspA4 were validated as potential biomarkers for breast cancer tissue." (PMID 31921692, 2019). "Other typical HSF1 targets upregulated by heat shock (e.g., HSPA1A, HSPA1B, HSP90AB1) showed higher expression levels in all HSF1high breast cancers." (PMID 36010586, 2022). "Finally, we validated that RAD9A, HSPA1B, GATA2, IGF2R, CD200, ERCC8, and BCL11A genes are consistently dysregulated in the doxorubicin-induced human-induced pluripotent stem cell-derived cardiomyocytes (hiPSC-CMs) derived from breast cancer patients." (PMID 37684436, 2023). "Finally, we validated the expression level of immune-related genes in breast cancer patients-derived cardiomyocytes with doxorubicin-induced cardiotoxicity and found that the level of RAD9A, HSPA1B, GATA2, IGF2R, CD200, ERCC8, and BCL11A genes are consistently dysregulated." (PMID 37684436, 2023).
hepatocellular carcinoma (5 papers, 2011 to 2024). A malignant tumor that arises from hepatocytes. "In hepatocellular carcinoma (HCC), expression of HSPA1B increased through Hepatitis B virus-mediated activation of ATF7, which accelerated cell proliferation by inhibiting apoptosis." (PMID 38461240, 2024). "Recently, single-cell profiling analysis of human CD127+ innate lymphoid cells from human patients with hepatocellular carcinoma (HCC) revealed that HSPA1A and HSPA1B expression were highly activated in late-state HCC, suggesting HSPA1B is important in tumor microenvironment remodeling." (PMID 38786053, 2024). "We performed the same experiment using the rat hepatoma FTO cell line and observed the same effect of LA induced Hspa1b promoter activity at the physiological temperature (not shown)." (PMID 21663599, 2011).
viral infection (5 papers, 2021 to 2025). "In our study, duplicated genes, that is, hsp70 (hspa1a) and hspa1b, were differentially expressed under five stress conditions (heat-, salinity-, and parasitic, bacterial, and virus infection-related stress conditions)." (PMID 37046999, 2023). "Studies have shown that HSPA1B inhibits viral proliferation in a viral infection's middle and late stages." (PMID 36276864, 2022). "HSPA1B belongs to the HSP70 family whose expression level is known to increase rapidly during cell stress (such as heat shock) or viral infection." (PMID 34961819, 2021). "One study revealed that HSPA1B can inhibit viral proliferation following viral infection." (PMID 41009536, 2025). "We identified 31 differentially expressed circRNAs and 7 mRNAs (HSPA8, HSPA1B, EGR2, CXCR4, SOCS3, NOTCH3, and ZNF527) related to viral infection." (PMID 41471859, 2025).
lung carcinoma (4 papers, 2019 to 2022). "The functional HSPA1B rs2763979 and rs6457452 variants are associated with lung cancer risk and survival." (PMID 32848724, 2020). "Analogously, genes involved in wound healing and cell migration (i.e., SERPINE1, HMGCR, IGFBP5, and S100A14) or reported as prognostic factors in breast, ovarian, gastric, and lung cancers (i.e., MAPRE1, HSPA1B, and PPME1) were negatively modulated." (PMID 31752957, 2019).